DLX5 (distal-less homeobox 5)
Diseases named in the same sentence as DLX5 in open-access papers (continued):
Sharing a sentence is not in itself a finding about the gene and the disease.
odontogenic cyst (1 paper, 2025). A cyst in the jaw that arises from tissues of tooth development. "Incorporating Dlx-5 and HLX expression analyses could enhance diagnostic accuracy, guide treatment decisions, and improve prognostic evaluations for patients with odontogenic cysts." (PMID 40003710, 2025). "Furthermore, it was considered that the expression of Dlx-5 and HLX might help reveal the behavioral differences between odontogenic cysts." (PMID 40003710, 2025). "Consequently, it is hypothesized that the detection of Dlx-5 and HLX expression in odontogenic cysts may exert a positive influence on treatment planning and prognostic predictions." (PMID 40003710, 2025).
OFCD syndrome (1 paper, 2022). "A total RNA microarray revealed alterations in the expression of numerous genes in BCOR Mut PDL cells, several of which are implicated in transcriptional upregulation; NFIB, DLX5, and ZFPM2 were the most significantly upregulated genes in OFCD syndrome." (PMID 35957990, 2022).
Ollier disease (1 paper, 2012). A rare primary bone dysplasia disorder characterized by the development of multiple mainly unilateral or asymmetrically distributed enchondromas throughout the metaphyses of the long bones. "DLX5 has also been shown to be differentially methylated and under-expressed in enchondromas from patients with Ollier disease, which is a non-hereditary skeletal disorder." (PMID 23144859, 2012).
orofacial cleft (1 paper, 2014). A disorder of facial skeleton that is characterized by cleft lip and/or cleft palate that result in feeding, speech and hearing problems caused by failures during development. "Nine noncoding sequence variants were identified within DLX5 and DLX6 of human patients with orofacial clefts." (PMID 24699068, 2014).
ovarian tumors (1 paper, 2025). "Research indicates that Dlx5 induces tumor formation and development in various cancers, including lung, uterine, and ovarian tumors, by promoting cell proliferation, differentiation, and apoptosis, as well as facilitating metastasis." (PMID 40003710, 2025).
periodontitis (1 paper, 2016). An acute or chronic inflammatory process that affects the tissues that surround and support the teeth. "Among them, DLX5 was found to be inactivated in PAFs derived from the adult periodontitis-affected gingival tissues." (PMID 27645561, 2016). "Furthermore, we identified DLX5 regulating expression of the long variant of RUNX2 transcript, which was specifically active in GFs but not in their periodontitis-affected counterparts." (PMID 27645561, 2016).
prostate carcinoma (1 paper, 2020). A carcinoma that arises from epithelial cells of the prostate gland. "Furthermore, it was here demonstrated that through its ability to target both RUNX2 and Dlx5, miR-203 decreases the expression of osteopontin and osteocalcin in prostate cancer cells." (PMID 32230926, 2020). "It is noteworthy that human miR-203, down-regulated in bone metastatic prostate cancer cells, binds to the 3′UTR of Dlx5." (PMID 32230926, 2020).
radicular cysts (1 paper, 2025). "Expression: Dlx-5 showed moderate to strong immunoreactivity in the nuclei and cytoplasm of epithelial cells in radicular cysts." (PMID 40003710, 2025). "In dentigerous cysts, the intensity of Dlx-5 immunoreactivity in the epithelium was similar to that in radicular cysts; however, stronger levels were observed in some connective tissue cells, especially those involved in inflammatory cell infiltrations and connective tissue giant cells." (PMID 40003710, 2025).
renal fibrosis (1 paper, 2021). A final common manifestation of a wide variety of chronic kidney diseases characterized by glomerulosclerosis and tubulointerstitial fibrosis. "The inhibition of DLX5 in a uremic model of renal fibrosis causes a decreased expression of Notch receptors, ligands, and target genes." (PMID 33498390, 2021).
rheumatoid arthritis (1 paper, 2018). A chronic, systemic autoimmune disorder characterized by inflammation in the synovial membranes and articular surfaces. "IPA of annotated transcripts showed similar activation of osteogenic-associated pathways such as roles of osteoblasts, osteoclasts, and chondrocytes in rheumatoid arthritis as well as the expression of typical osteogenic genes such as dlx5, tsc22d3, alpl, klf4, ext1, and stc1 in both datasets." (PMID 30376879, 2018).
scoliosis (1 paper, 2025). A congenital or acquired spinal deformity characterized by lateral curvature of the spine. "Disruptions in the activities of Sox9+, Fgfr3+, or Dlx5+ progenitors at E10.5 may underlie osteogenic conditions such as scoliosis or long-bone deformities." (PMID 40581360, 2025).
tumor (22 papers, 2010 to 2025). "Mechanistically, lncRNA RP11-197K6.1 acted as a molecular sponge for miR-135a-5p, thereby alleviating miR-135a-5p-mediated suppression of DLX5, a key transcription factor implicated in tumor progression." (PMID 38760791, 2024). "DLX5 regulates the expression of MMPs, which are enzymes involved in degrading the extracellular matrix and facilitating tumor cell invasion." (PMID 40858590, 2025). "Previous studies have confirmed that the overexpression of DLX5 can promote tumor cell growth by directly targeting the c-MYC gene." (PMID 38760791, 2024). "According to previous research, the overexpression of DLX5 can promote tumor cell growth by directly targeting the c-MYC gene." (PMID 38760791, 2024). "Previous studies have confirmed that DLX5, a transcription factor, is closely related to tumor progression, and its upregulation in various tumors is usually associated with poor prognosis in patients." (PMID 38760791, 2024). "DLX5 plays an important role in tumor proliferation and metastasis and is upregulated in various cancers." (PMID 38760791, 2024). "It promoted the migration and metastasis of CRC cells by interacting with miR-135a-5p, alleviated suppression of DLX5 expression, and facilitated tumor growth." (PMID 38760791, 2024). "CKS1B+ neoplasm, CST6+ neoplasm and MTND2P13+ neoplasm are more prevalent in advanced LUAD, while DLX5+ neoplasm is more common in early‐stage LUAD." (PMID 38946232, 2024). "Such silencing of DLX5 is associated with a lower rate of complete remission and poorer overall survival, suggesting a tumor suppressing role of DLX5 in AML and MDS." (PMID 34203994, 2021). "DLX5 potentiated AKT signaling to promote tumor cell proliferation, and knockdown of DLX5 reduced cell viability and downregulated IRS-2 and AKT phosphorylation." (PMID 34203994, 2021). "DLX5 has been shown to stimulate tumor cell proliferation through upregulation of the MYC expression." (PMID 31093489, 2019). "In NSCLC, DLX5 has been reported to be overexpressed at the mRNA and protein level, and correlated with tumor size and poor prognosis." (PMID 30412601, 2018). "Instead, the increased gene transcript levels in tumor cells appeared to result from increased interaction between Notch promoters and Dlx5-bound Notch enhancers, as revealed by CCC assay." (PMID 28122332, 2017). "Dlx5 knockdown resulted in reduced tumor cell viability/proliferation and an increased population of apoptotic sub-G1 cells due, in part, to down regulation of phospho-Akt and/or Notch1/3." (PMID 28122332, 2017). "This reactivation of Dlx5 was proposed to facilitate tumor development by interfering with T-cell differentiation and providing a second “hit” critical in the malignant transformation of thymocytes." (PMID 28122332, 2017). "Deregulation of the expression of Dlx genes, including Dlx-4 and Dlx-5, was found in human solid tumors and hematologic malignancies and indicates an important role(s) of Dlx in tumor growth and progression." (PMID 21917150, 2011). "Dlx-5 has been shown to promote tumor cell proliferation by directly binding the MYC promoter and upregulating MYC." (PMID 21917150, 2011). "Among the top features were also other fibroblast-associated TF like SP7, RUNX2, and DLX5, which could suggest CAF-mediated collagen production at the tumor site." (PMID 39161957, 2024). "Additionally, a xenograft mouse model was used to study the in vivo effects of lncRNA RP11-197K6.1 on tumor growth, and an immunohistochemical assay was performed to assess DLX5 expression in tumor tissues." (PMID 38760791, 2024).
tumor (continued). "GBM has also been found to induce WNT5A to mediate tumor cell differentiation into endothelium-like cells via the PAX6/DLX5 transcription program, and subsequently recruit peripheral endothelial cells, which form pseudo-blood vessels, thereby facilitating tumor-invasive growth." (PMID 36880534, 2023). "Moreover, upregulation of Vegf and down-regulation of many apoptosis-related genes and Jak-Stat genes were seen only in tumor cells from Lck-Dlx5;Lck-MyrAkt2 mice." (PMID 32985581, 2020). "Tumor onset was greatly accelerated in Lck-Dlx5;Lck-MyrAkt2 transgenic mice, with median survival being only 8 weeks versus 24 weeks in Lck-MyrAkt2 mice and 39 weeks in Lck-Dlx5 mice." (PMID 32985581, 2020). "We found that 14% of genes showed ASE in one or more cell lines and identified allelic switching of the potential cell survival genes DLX5, GRB10, and SVOPL on chromosome 7, whereby the most abundantly expressed allele in the normal tissue is the lowest expressed allele in the tumor and vice versa." (PMID 31093489, 2019). "We found that Dlx5 expression was required for tumor growth in vivo and that knockdown of Dlx5 could be partially rescued by expression of either NIC3 or MyrAkt2." (PMID 28122332, 2017). "Thus, in both Lck-MyrAkt2 mice and Lck-Dlx5 mice, tumor formation appears to require cooperation between Akt and Dlx5 or Myc." (PMID 28122332, 2017). "Moreover, combinational treatment of Lck-Dlx5 tumor cells with GSK690693 and DAPT or γ-secretase inhibitor XXI resulted in a marked increase in cell death as shown by augmentation of the sub-G1 peak and by activation of caspase-3." (PMID 28122332, 2017). "Thus, we concluded that Dlx5 directly transactivates Notch1/3 genes and promotes β-selection escape, which eventually results in tumor formation." (PMID 28122332, 2017). "We now report that Notch1/3 expression and Akt signaling are activated throughout T cell development in Lck-Dlx5 mice, and that tumor formation is associated with further intensification of Notch and Akt signaling." (PMID 28122332, 2017). "In addition, Dlx-5 is also unregulated in several human solid tumors, including lung, breast, and ovarian cancers, and T-cell lymphomas, and contributes to tumor progression." (PMID 21917150, 2011). "It is interesting to note that in situ hybridization on bone metastases showed an increased DLX5/6 expression signal intensity in tumor cells in close contact with the bone tissue, suggesting a correlation between expression of these genes and the invasion front." (PMID 21108812, 2010). "However, recently published microarray studies demonstrated the upregulation of DLX5 in several human solid tumors, suggesting that overexpression of DLX5 could contribute to tumor progression and represent a novel prognostic marker." (PMID 21108812, 2010). "We also noted that DLX5 played an important role in the progression of CRC, was highly expressed in tumor tissues, and was negatively correlated with the overall survival rate." (PMID 38760791, 2024). "Deregulation of DLX genes, including DLX4 and DLX5, was found in human solid tumors and hematologic malignancies, which indicated that DLX played an important role in tumor growth and progression." (PMID 26052251, 2015). "The aberrations of three selected genes, CXCL5, DLX5 and RUNX2, were validated in five cell lines and five tumour samples using PCR techniques." (PMID 23144859, 2012). "Changing patterns of ASE in normal and tumor tissues suggests that ASE of DLX5 and SVOPL is not parent-of-origin-specific." (PMID 31093489, 2019). "Immunoblot analysis revealed that non-malignant thymic T cells from Lck-Dlx5 mice have significantly less activation of caspase-3 than tumor cells." (PMID 28122332, 2017). "Dlx5 was required for tumor maintenance via its activation of Notch and Akt, as tumor cells were highly sensitive to Notch and Akt inhibitors." (PMID 28122332, 2017).
tumor (continued). "As for RUNX2, none of the tumour samples showed gain of DLX5, but all showed increased expression at similar levels as the cell lines showing over-expression." (PMID 23144859, 2012). "Interestingly, the only Lck-Dlx5 tumor (1/11) without overexpression of Notch1 and Notch3 instead showed upregulation of Notch2, further suggesting an essential role for aberrant Notch signaling in Dlx5-driven T-cell lymphomagenesis." (PMID 28122332, 2017). "However, both AML and MDS are heterogeneous diseases, and DLX5 methylation pattern were not analyzed in single tumor cell population such as CD34+ cell population, leading to a huge difference of DLX5 methylation in patients with AML and MDS." (PMID 32508046, 2020).
cancer (15 papers, 2010 to 2025). A tumor composed of atypical neoplastic, often pleomorphic cells that invade other tissues. "Dysregulation of DLXs including DLX5 caused by DNA methylation in various cancers potentially served as therapeutic targets." (PMID 32508046, 2020). "DLX5 is one of six DLX family members expressed during embryonic development but has also been implicated in a number of cancers." (PMID 30412601, 2018). "Our study found that DLX5 mainly upregulates metabolic pathways, accelerating metabolic cycles in the cancer microenvironment and helping cancer cells grow and proliferate more effectively." (PMID 40244296, 2025). "The genes that showed the highest variation in methylation, distal-less homeobox 5 (DLX5) and tumour protein 73 (TP73), are genes that are both linked to cancer development." (PMID 26220712, 2015). "DLX5 has also been reported to be involved in cancer, organ fibril formation, and inflammation." (PMID 39539538, 2024). "All these results suggested that the function of DLX5 may be specific in different cancer types, and further studies are required to evaluate the biological functions in diverse human cancers." (PMID 32508046, 2020). "However, several studies indicated the oncogenic role of DLX5 in other human cancers." (PMID 32508046, 2020). "With the development of personalized medicine and precision medicine, therapeutic strategies based on the lncRNA RP11-197K6.1/miR-135a-5p/DLX5 axis are expected to provide more precise and effective treatment options for CRC and other cancers." (PMID 38760791, 2024). "In future studies, given that the role of the lncRNA RP11-197K6.1/miR-135a-5p/DLX5 axis in CRC has been clarified by this study, it is particularly important to further explore its potential role in other types of cancers." (PMID 38760791, 2024). "For other genes or regions, e.g. DLX5, GRASP Region 3, IRX1, MMP2, NPY, PDX1 and TCF21, significant levels of methylation were evident in the matched normal tissue but methylation was always significantly increased in the cancer tissue." (PMID 24485021, 2014). "In particular DLX5 overexpression, together with concomitant DLX2 downregulation, could identify a subset of more aggressive cancers that would need a different treatment and a more careful follow-up." (PMID 21108812, 2010).
infection (6 papers, 2018 to 2023). The state of being infected such as from the introduction of a foreign agent such as serum, vaccine, antigenic substance or organism. "The specific expression levels of Pax2, Pax8, Eya1, Six1, and Dlx5 in cells from the J1-6d infection scheme were significantly lower than those in the cells infected with NC-shRNA, as shown by semi-quantitative RT-PCR (p < 0.01)." (PMID 34940631, 2021). "Infection with Ad-h-DLX5 increased DLX5 transcripts ~231-fold in CPCL3." (PMID 32650430, 2020). "Moreover, infection-induced immune cross-reactions might have functional, spatial, and temporal implications related to the functions and expression patterns of DLX1 and DLX5 in the fetal and adult human brain." (PMID 29618965, 2018).
psychiatric diseases (2 papers, 2022 to 2024). "Together, our results suggest that genetic variations in the DNA regions governing Dlx5/6 brain expression could contribute to individual differences in cognition and, in certain cases constitute genetic risk factors for psychiatric diseases." (PMID 35681437, 2022).
DLX5 also shares sentences with these, for which no sentence is quoted: colorectal cancer (4 papers); epilepsy (2); hematologic malignancies (2); acute myeloid leukemia (1); adenoma (1); Alzheimer disease (1); attention deficit-hyperactivity disorder (1); Bosch-Boonstra-Schaaf optic atrophy syndrome (1); Brachycephaly (1); brain tumors (1); campomelic dysplasia (1); cyst (1); diabetes (1); glioma (1); hepatocellular carcinoma (1); inguinal herniae (1); melanoma (1); mitral valve prolapse (1); musculoskeletal disorder (1); Nager syndrome (1); neurodevelopmental disorder (1); neurological disorders (1); odontogenic tumor (1); Osteopenia (1); personality disorder (1); premature ovarian failure (1); Seizure (1); skeletal dysplasia (1); small cell lung carcinoma (1); split-hand/split-foot malformation 4 (1).
A further 3 diseases each share a sentence with DLX5 in 1 paper.